EGFR (epidermal growth factor receptor)
Diseases named in the same sentence as EGFR in open-access papers (continued):
Sharing a sentence is not in itself a finding about the gene and the disease.
hepatocellular carcinoma (continued). "Here the authors identify a lncRNA that, through direct interactions with EGFR, promotes T-regulatory cell differentiation within the microenvironment of hepatocellular carcinoma, thus promoting tumour growth via immune suppression." (PMID 28541302, 2017). "GALNT2, sharing a high amino acid sequence homology with GALNT14, regulates the malignant character of hepatocellular carcinoma by modulating the structure of short O-glycans on EGFR." (PMID 28388560, 2017). "Taking HCC as an example, lncRNA lnc-EGFR links an immunosuppressive state to cancer by promoting Treg cell differentiation, and promotes hepatocellular carcinoma immune evasion." (PMID 29179477, 2017). "Cell surface GRP78 directly bound to and phosphorylated c-src for EGFR activation, promoting the invasion and metastasis of hepatocellular carcinoma (HCC) cells, and accelerating the proliferation and migration of breast cancer cells by activating STAT3." (PMID 29069845, 2017). "The tyrosine kinase inhibitor erlotinib targets the receptor of epidermal growth factor (EGFR) involved in development of hepatocellular carcinoma (HCC)." (PMID 28915658, 2017). "After systemic application of these polymers condensed with NIS DNA, tumor-specific radioiodide accumulation demonstrated effective and EGFR-specific tumor targeting in a high EGFR-expressing xenograft mouse model of hepatocellular carcinoma." (PMID 28380420, 2017). "The interplay between YAP1 and EGFR signaling was noted previously where EGFR activation induced YAP1 gene expression in a study of hepatocellular carcinoma, while YAP1 induced EGFR expression in another report." (PMID 26716514, 2016). "The tumors with the greatest number of patients (n > 6): NSCLC, nasopharyngeal, colorectal, renal and liver carcinoma showed co-expression (EGFR/NeuGcGM3) in more than 50 % of their tumoral cells." (PMID 27449755, 2016). "In tumorigenesis, BAIAP2L1 has been reported to promote cell proliferation through activation of the EGFR-ERK pathway in hepatocellular carcinoma." (PMID 26222696, 2015). "The binding of HCV to human hepatoma cells induces EGFR activation which is dependent on the interactions between HCV and CD81." (PMID 25757571, 2015). "Intriguingly, to overcome IGF-1R inhibition, hepatoma cells were able to activate ErbB3 in an EGFR-dependent manner." (PMID 26729094, 2015). "BAIAP2L1 is recently reported to promote cell proliferation through activation of the EGFR-ERK pathway in hepatocellular carcinoma." (PMID 26222696, 2015). "Because evasion of apoptosis contributes to treatment resistance in hepatoma, our results also support further investigation of combined therapeutic blockade of EGFR and SOS1." (PMID 25980493, 2015). "The treatment of hepatocellular carcinoma (HCC) cells with EGFR-specific tyrosine kinase inhibitors or neutralizing antibodies induces cell cycle arrest and apoptosis and increases chemosensitivity." (PMID 24853453, 2014). "EGFR and fos are involved in biological processes including neurogenesis, neuron differentiation, and neuron development, and also breast neoplasm and hepatocellular carcinoma." (PMID 25563226, 2014). "In vitro experiments revealed ligand-independent MET activation through EGFR-MET co-immunoprecipitation in hepatocellular carcinoma cells and promotion of metastatization by MET and IGF-1R cross-talk in pancreatic cancer." (PMID 28548075, 2014). "This was noted in hepatocellular carcinoma lines, in which resistance to anti-IGF-1R treatment was associated with increased signaling through EGFR pathways, and that this resistance was overcome by targeting both IGF-1R and EGFR." (PMID 23548153, 2013). "A recent study has implicated PI3 kinase/Akt signaling in hypoxia-induced EMT in hepatocellular carcinoma cells and EGFR is required for the Akt activation." (PMID 23185433, 2012). "EGFR overexpression has been detected in several human cancers such as breast, gut, and hepatocellular carcinoma." (PMID 23319880, 2012).
hepatocellular carcinoma (continued). "Taken together, these results suggest that the PGE2-induced transactivation of EGFR in MH1C1 hepatoma cells is mediated primarily by FP receptors and signalling via Gq and PLCβ." (PMID 22967907, 2012). "Recent studies indicated that EGFR is frequently expressed in human hepatoma cells, and EGF is one of the mitogens that is needed for the growth of hepatoma cells." (PMID 22860012, 2012). "Treatment with acyclic retinoid produces a dual activation of caspase 3 and TG2 induced apoptosis of hepatocellular carcinoma cells via modification and inactivation of Sp1, resulting in reduced expression of epidermal growth factor receptor." (PMID 21214951, 2011). "In the setting of chronic liver injury in humans, epidermal growth factor (EGF) and EGF receptor (EGFR) are up-regulated and have been proposed to have vital roles in both liver regeneration and development of hepatocellular carcinoma (HCC)." (PMID 20618941, 2010). "It has been found that the overexpression of kinase-inactive ILK increases the sensitivity of EGFR-resistant hepatoma cell lines to the EGFR inhibitors erlotinib, gefitinib and cetuximab in vitro and in vivo." (PMID 21060779, 2010). "In our study, we sought to determine if similar respective gain-of-function EGFR and ERBB2 mutations were present in hepatoma and/or biliary cancers." (PMID 17150109, 2006). "In our study, we sought to determine if similar respective gain-of-function EGFR and ERBB2 mutations were present in hepatoma and biliary cancers to determine the potential for ERBB -targeted therapy." (PMID 17150109, 2006). "Recently, we have shown that gefitinib is effective in inhibiting intrahepatic metastasis of murine hepatocellular carcinoma CBO140C12 cells by blocking EGFR-dependent metastatic properties." (PMID 15841081, 2005). "We have previously reported that gefitinib inhibits the spontaneous intrahepatic metastasis of hepatocellular carcinoma by blocking the EGFR-mediated metastatic properties." (PMID 15841081, 2005). "SNX16 has previously been described as acting as an oncogene in hepatocellular carcinoma, promoting tumor aggressiveness through the EGFR–AKT pathway, and its inhibition has been proposed to offer therapeutic benefits by blocking tumor cell proliferation and invasion." (PMID 40863222, 2025). "Similarly, the enhancement of EGFR and VEGFA translation in lenvatinib‐resistant hepatocellular cancer has been linked to METTL1 activity." (PMID 39979979, 2025). "Similar reports have been limited to the efficacy of ICL combined with bevacizumab in patients with advanced cholangiocarcinoma, hepatocellular carcinoma, and cervical carcinoma, mostly focusing on the inhibition of PD‐1 expression, ALK positivity, and EGFR mutation, and so forth." (PMID 40488279, 2025). "Through this study, we preliminarily confirmed that Ansofaxine hydrochloride has the effect of inhibiting hepatocellular carcinoma cell growth and may be closely related to inhibiting EGFR/MAPK." (PMID 40809022, 2025). "MiR-486-3p inhibits the proliferation, migration, and invasion of retinoblastoma, inhibits the proliferation and metastasis of cervical cancer, targets FGFR4 and EGFR to mediate drug resistance in hepatocellular carcinoma, and reverses the malignant phenotype of GBM cells." (PMID 38725030, 2024). "CASC4 has a paralog, GOLM1 (GOLPH2, GP73), which is a driver of hepatocellular carcinoma through various pathways, including cholesterol-dependent recycling of members of the erythroblastic oncogene B (ERBB) family of RTKs, such as the epithelial growth factor receptor 1 (EGFR/ERBB1) and ERBB4." (PMID 38030811, 2024). "PGE2 has been shown to induce Y box-binding protein 1 expression via activation of EP1-proto-oncogene tyrosine-protein kinase Src-epidermal growth factor receptor (EGFR)-p44/42 MAPK-mTOR pathway which increases the invasive ability of hepatocellular carcinoma cells." (PMID 39290706, 2024).
hepatocellular carcinoma (continued). "Additionally, the literature shows that Cx23 increases EGFR levels by upregulating Src expression and inhibits apoptosis in hepatocellular carcinoma cells by inducing activation of the EGFR signaling pathway." (PMID 38818039, 2024). "These bromobenzofuran-oxadiazole structural hybrids BF1-9 were evaluated in vitro against anti-hepatocellular cancer (HepG2) cell line as well as for their in silico therapeutic potential against six key cancer targets, such as EGFR, PI3K, mTOR, GSK-3β, AKT, and Tubulin polymerization enzymes." (PMID 36769327, 2023). "Interestingly, EGFL7 can also bind to the EGFR at cell membrane and this interaction enhances cell migration of hepatocellular carcinoma cells through FAK phosphorylation." (PMID 37853459, 2023). "Moreover, ITGB4 promotes metastasis of hepatocellular carcinoma by conferring anchorage independence through EGFR‐dependent FAK‐AKT activation." (PMID 36507553, 2023). "The influence of D. chrysotoxum on hepatocellular carcinoma inhibition may depend on making an impact on EGFR tyrosine kinase inhibitor resistance pathway and FoX O signaling pathway." (PMID 37393306, 2023). "In addition, there are reports stating that β3GnT2, a polylactosamine synthase, regulates glycosylation of EGFR in human hepatocellular carcinoma cells." (PMID 35393406, 2022). "Hypoxia-induced YTH-domain family 2 (YTHDF2) is reported to inhibit hepatocellular carcinoma (HCC) growth via destabilizing EGFR mRNA, which may contribute to resistance to tumorigenesis in a hypoxic environment." (PMID 35794625, 2022). "Moreover, PLAGL2 overexpression plays a vital role in hepatocellular carcinoma and induces tumor metastasis via EGFR-HIF-1/2α signaling, and cell lines with high PLAGL2 expression have erlotinib resistance, which can be a biomarker for erlotinib therapy." (PMID 35565203, 2022). "It is worth noting that our key gene, namely EGFR, has been shown to play a key role during liver regeneration following acute and chronic liver damage, as well as in cirrhosis and hepatocellular carcinoma, highlighting the importance of EGFR in the development of liver diseases." (PMID 35745580, 2022). "Activation of EP4 also upregulates snail protein via EGFR to promote migration in hepatoma cells." (PMID 35356289, 2022). "Furthermore, ITGB4 cooperates with EGFR to foster resistance to anoikis in hepatocellular carcinoma." (PMID 36076232, 2022). "Consistent with a role for ILK in mediating EGFR tyrosine kinase inhibitor (TKI) resistance, xenograft models of EGFR inhibitor-resistant human hepatocellular carcinoma cell lines found that inhibiting ILK activity increased the sensitivity of cells to EGFR inhibition." (PMID 34373451, 2021). "The EGFR pathway is essential in liver regeneration, cirrhosis, and hepatocellular carcinoma." (PMID 34579396, 2021). "Interestingly, Reactome representation based on Boolean network modeling confirmed that the EGFR pathway was among the most enriched pathways by compounds 10 and 29; this pathway is vital in liver regeneration and hepatocellular carcinoma development." (PMID 34579396, 2021). "By detecting an increase of phosphorylated EGFR in the nucleus, we validated our proposed model: As a result of the active TP form of SOF in hepatoma cells, EGFR is activated and translocated into the nucleus, where it enhances the transcription of pro-survival genes." (PMID 32316635, 2020). "However, other studies show that YTHDF2 suppresses cell proliferation and growth via destabilizing the EGFR mRNA in hepatocellular carcinoma." (PMID 33505426, 2020). "Hepatocellular carcinoma cell line (HLE) was used to evaluate EGFR inhibition by 17-AAG." (PMID 33537004, 2020). "In hepatocellular carcinoma, EGFR and c-MET cooperate to enhance resistance to PARP inhibitors." (PMID 32093123, 2020).
hepatocellular carcinoma (continued). "As Y-box is presented in the promoter of many genes, including multidrug-resistant 1, epidermal growth factor receptor, DNA polymerase, and thymidine kinase, YB-1 promotes tumor cell proliferation and is considered as a tumor marker of human hepatocellular carcinoma." (PMID 32029232, 2020). "Therefore, we first determined the expression and activation of EGFR in hepatoma cells such as PLC/PRF/5, HCC-LM3, HepG2, Hur7, SMMC-7721 cells." (PMID 32298294, 2020). "Blocking EGFR degradation induces the proliferation of CC cells through prolonged EGFR activation-mediated COX-2/prostaglandin (PGE2) signaling relative to other hepatoma cells, and PGE2 as a downstream product of COX-2 prevents EGFR inhibitor-mediated growth suppression in CC cells." (PMID 32708604, 2020). "Furthermore, EGFR activation has been proven to be a potential determinant of primary resistance of hepatocellular carcinoma cells to sorafenib." (PMID 32190291, 2020). "Additionally, upon ligand (EGF and TGF) binding, EGFR activates tyrosine kinases on the cell surface, which leads to the disordered growth of hepatoma cells." (PMID 31684985, 2019). "Furthermore, B4GALT1 interacts directly with EGFR inhibiting the dimerization of the receptor and the tyrosine phosphorylation and its activation in human hepatocellular carcinoma cells, suggesting an inhibitory role of B4GALT1 in EGFR signaling pathway." (PMID 31635093, 2019). "Furthermore, the analysis of human hepatocellular carcinoma specimens obtained from the GEO database showed that the expression of EGFR and Met correlated with that of Grb2." (PMID 29575431, 2018). "This is in contrast to our previous findings in colorectal and hepatocellular carcinoma, where EGFR expression in myeloid cells was found to be essential for tumor formation, indicating that the tumorigenic role of EGFR varies depending on the tumor and cell type." (PMID 30361264, 2018). "The EGFR pathway plays an important role in promoting hepatocellular carcinoma (HCC) metastasis." (PMID 27906672, 2017). "In this sense, although IRA overexpression has been found in tumour samples of hepatocellular carcinoma, it seems that is not a causal factor but a consequence of the activation of other pathways such as EGFR." (PMID 27562101, 2016). "We have previously shown that dysregulation of GALNT2 contributes to the malignant progression of hepatocellular carcinoma and oral squamous carcinoma cells by modifying glycosylation of the epidermal growth factor receptor, a member of receptor tyrosine kinase (RTK) family." (PMID 26848976, 2016). "The expression of intratumoral and peritumoral Casitas B-lineage Lymphoma (cb1) and epidermal growth factor receptor (EGFR) in hepatocellular carcinomas (HCCs) followed by curative resection was assessed by tissue microarray-based immune-histochemistry in two independent cohorts (n = 352)." (PMID 26474280, 2015). "Additionally, C/EBPβ expression is upregulated by Epidermal Growth Factor Receptor (EGFR) in oral carcinomas and esophageal squamous cell carcinomas due to endoplasmic reticulum (ER) stress in hepatoma cells." (PMID 25965830, 2015). "Additionally, inhibition of EGFR in different animal models by Erlotinib was shown to attenuate liver fibrosis and the development of hepatocellular carcinoma thus suggesting new therapeutic intervention strategies in the prevention of HCC." (PMID 25872475, 2015). "FLCs also show overexpression of the EGFR and the mTOR pathways, both pathways which are also commonly over-expressed in typically hepatocellular carcinomas and may have therapeutic possibilities." (PMID 24278737, 2012). "Studies have indicated that EGFR/HER1 is actively expressed in human hepatoma." (PMID 21985599, 2011). "All hepatoma and biliary cancers samples were negative for gain-of-function somatic mutations affecting the catalytic domain of the EGFR gene." (PMID 17150109, 2006).
hepatocellular carcinoma (continued). "Studies indicate that EGFR is expressed in up to 85% and 80% of hepatoma and biliary cancers, respectively, and EGF might be required for the growth of those cells." (PMID 17150109, 2006). "Several groups described a link between EGFR signaling and the Hippo pathway in relation to the development of cancer, including in hepatocellular carcinoma (HCC), lung cancer and breast cancer." (PMID 39936032, 2025). "In contrast to its oncogenic roles, in hepatocellular carcinoma (HCC), MAOA was linked to better patient prognoses and was found to suppress metastasis by inhibiting the adrenergic system and its transactivation of epidermal growth factor receptor (EGFR) signaling." (PMID 41338163, 2025). "A study found that LPS stimulation in mice increased EREG expression in tumor tissues, which enhanced tumor angiogenesis via IL-8 signaling and promoted the migration and invasion of EGFR-positive hepatocellular carcinoma (HCC) cells." (PMID 39948481, 2025). "In conjunction with α2M*, membrane-associated GRP78 in hepatocellular carcinoma (HCC) cells is capable of interacting directly with Src, a tyrosine kinase, stimulating its phosphorylation and further facilitating the interaction between Src and epidermal growth factor receptor (EGFR)." (PMID 38646439, 2024). "lncRNA epidermal growth factor receptor (lnc‐EGFR) could specifically bind to tyrosine kinase receptor EGFR, thus promoting the differentiation of regulatory T cells and enhancing the immune escape function of hepatocellular carcinoma cells." (PMID 38764726, 2024). "The molecular cause of this process is unknown but could be related to nonreceptor site binding/activation of G protein subunit alpha q (GNAQ) or other impacts on epidermal growth factor receptor (EGFR), Src, and tyrosine kinase expressed in hepatocellular carcinoma (TEC) family kinases." (PMID 39345278, 2024). "For example, the protein 14‐3‐3σ has increased expression levels in hepatocellular carcinoma (HCC) tissues, actively facilitates the resistance to anoikis and the metastatic behaviour of HCC cells through the EGFR/ERK1/2 axis." (PMID 38332530, 2024). "Furthermore, PGRMC1 correlates with EGFR at mRNA level in patients with hepatocellular carcinoma." (PMID 37887342, 2023). "In hepatocellular carcinoma (HCC), one research shows that YTHDF2 expression has a positive correlation with HCC progression whereas another research reports that YTHDF2 suppressed HCC tumor growth through accelerating EGFR mRNA degradation." (PMID 36008805, 2022). "Further, hepatocellular carcinoma-related protein 1 (HCRP1), a protein responsible for degradation of ubiquitinated membrane receptors, is downregulated in HCC and correlated with increased EGFR activation, EMT, Snail and Twist1 expression." (PMID 34067095, 2021). "In particular, the EGFR pathway is critical in liver regeneration, cirrhosis, and hepatocellular carcinoma (HCC)." (PMID 34579396, 2021). "Ibrutinib inhibited EGFR signaling in sorafenib-sensitive and sorafenib-resistant hepatocellular carcinoma cells (HCC) and showed synergistic effects with sorafenib in an immune-competent mouse model of HCC." (PMID 32455989, 2020). "Among them, lnc-EGFR is highly expressed in Tregs of patients with hepatocellular carcinoma (HCC), where it acts as an activator of Tregs differentiation." (PMID 32549757, 2020). "The role of lnc-EGFR in Tregs was discovered in a hepatocellular carcinoma (HCC) study in which high throughput screening examined links between lncRNAs and mRNAs in HCC patient samples." (PMID 31336952, 2019). "Upregulation of EGFR signalling pathway in hepatocellular carcinoma (HCC) is supported by several lines of evidences." (PMID 28915658, 2017). "One study reported that sorafenib, a multikinase inhibitor, switches from HIF-1α- to HIF-2α-dependent pathways, resulting in resistance to sorafenib in hypoxic hepatocellular carcinoma (HCC) by activating the TGF-α/EGFR pathway." (PMID 28476028, 2017).